FOXM1 (forkhead box M1)
Diseases named in the same sentence as FOXM1 in open-access papers (continued):
Sharing a sentence is not in itself a finding about the gene and the disease.
cancer (continued). "FOXM1 (Forkhead Box M1) is a member of FOX family and located on the chr12p13.33, which emerged as a key molecule implicated in initiation and progression of cancer." (PMID 32696617, 2020). "Overall, these results indicate that the expression level of FOXM1 can be a prognostic marker for at least nine different cancer types, and the inhibition of FOXM1 may be an attractive strategy for cancer therapy." (PMID 32858881, 2020). "Additionally, the results showed that FOXM1, a well-known cancer related gene, is the direct target of the MIAT/miR-149-5p axis." (PMID 32742195, 2020). "Thus E6 upregulates FOXM1, activates the Wnt/β-catenin pathway, and initiates cancer carcinogenesis through the E6/MZF1/NKX2-1/FOXM1/β-catenin transcriptional factors axis." (PMID 32758292, 2020). "In addition to the regulation of cancer by these various transcriptional mechanisms, FOXM1 has been shown to exert its role in cancer development by several critical protein-protein interactions." (PMID 33680951, 2020). "In general, FoxM1 overexpression is closely related to high proliferation rate and late tumor stage, and may serve as a prognostic marker for numerous human cancers." (PMID 31992359, 2020). "E2F1 and FOXM1 are two well-studied genes involved in cancer." (PMID 33396205, 2020). "Subsequent investigations revealed that FoxM1 served as a critical modulator of multiple other cellular processes such as cell proliferation and differentiation, apoptosis and DNA damage repair, thus promoting pathogenesis of human cancers and other disorders." (PMID 33179861, 2020). "FOXM1 is involved in tumor cell proliferation and is overexpressed in numerous types of cancers." (PMID 32679860, 2020). "Accordingly, we have tried to discover FoxM1 inhibitor from medicinal plants as anti-cancer agents." (PMID 32429421, 2020). "A large amount of literature exists regarding FOXM1’s role in homeostasis and tumorigenesis, which the current review summarizes by primarily focusing on the altered upstream and downstream regulatory mechanisms in cancer." (PMID 33680951, 2020). "However, recent studies have shown abnormal overexpression of FOXM1 in various cancer tissues, such as those of the bladder, liver, prostate, brain, breast, lung, colon, pancreas, skin, cervix, ovary, and mouth." (PMID 32486251, 2020). "In conclusion, RAME induced accelerated anti-cancer effects by regulating FOXM1 expression levels, and it could be considered to be a potential anticancer therapeutic." (PMID 33053721, 2020). "These genes are known to be under direct transcriptional control by FOXM1 in different cancers." (PMID 32961773, 2020). "Given that FoxM1 is one of target genes for miR-320d, we speculate that FoxM1-mediated signaling pathways can be responsible for tumorigenesis, metastasis, and drug-resistance in malignant tumor development following dysregulation of miR-320d." (PMID 32551039, 2020). "This review sheds light on how integral and inherent FOXM1 is in the pathogenesis of cancer." (PMID 33680951, 2020). "Forkhead Box M1 (FOXM1) has been involved in malignant behaviors of cancer." (PMID 33291076, 2020). "Elevated FOXM1–LDHA signaling increased cancer cell growth and metastasis." (PMID 32093417, 2020). "Intriguingly, several circRNAs are supported to function in cancers via regulating FOXM1." (PMID 32513952, 2020). "Furthermore, FOXM1, as the downstream target, is frequently involved in the regulation of cancer progression." (PMID 32514270, 2020). "FoxM1 expression is found to be upregulated in a number of human cancers, including CRC." (PMID 31992359, 2020). "Recent studies on FOXM1 miRNAs have revealed several prospective targets for cancer treatment." (PMID 33680951, 2020).
cancer (continued). "Furthermore, in cancer, NEK2 is targeted by FOXM1, and it has been shown to cause drug resistance in MM and some other malignancies." (PMID 32679860, 2020). "Recently, FOXM1 has been reported to contribute to radioresistance in several carcinomas." (PMID 32595418, 2020). "In addition, these studies reveal that Cyclin E1 is an upstream activator of FOXM1 expression in human cancers, including HGSC." (PMID 30795624, 2019). "Moreover, the activation of transcription factors is regulated by upstream signaling pathways, such as Akt and Erk, which are critical for the biological functions of FOXM1 in cancer progression." (PMID 30367545, 2019). "Comparing across cancer types, there was a broad spectrum of FOXM1 expression, suggesting that high FOXM1-expressing cancers may have unique genetic features that drive increased FOXM1 expression." (PMID 30795624, 2019). "Additionally, studies of FOXM1 isoform expression have focused on a single or limited number of cancer types, warranting a need for a comprehensive analysis using normal and cancer tissues." (PMID 30795624, 2019). "However, analysis of TCGA paired normal and tumor showed that all three FOXM1 isoforms have relatively equivalent increases in paired cancer vs. normal tissues." (PMID 30795624, 2019). "FOXM1 was shown to reduce the sensitivity of cells to anti-cancer drugs, such as cisplatin and paclitaxel, in an in vitro model, and its overexpression in tumor tissues is a predictor of cancer progression and an unfavorable prognostic factor." (PMID 30885238, 2019). "In these studies, experimental results from FOXM1 knockout mice and in vitro studies in which FOXM1 was inhibited by a using pharmacologic agent (i.e., thiostrepton) or gene knockdown support the concept that FOXM1 contributes to the oncogenicity of these cancers." (PMID 31390744, 2019). "FOXM1 mRNA expression was increased in all TCGA cancer types compared to GTEx and TCGA normal." (PMID 30795624, 2019). "Aurora‐A‐mediated stabilization of FOXM1 could reflect its kinase‐independent role in enhanced proliferation capacity of TNBC cancer cells." (PMID 31359594, 2019). "FOXM1 is located at chromosome 12p13.33, an amplified region in cancer." (PMID 30795624, 2019). "Moreover, O-GlcNAcylation mediated SIRT1 stability in cancer cells directly affected the proteasome degradation of oncogenic transcription factor FOXM1." (PMID 31881804, 2019). "FOXM1 is also a promising therapeutic target for cancer treatment." (PMID 30795624, 2019). "Given the potential role of FOXM1 as a molecular partner of HMGA1, we searched for a relationship between HMGA1 and FOXM1 in The Cancer Genome Atlas (TCGA), a public database collecting information from a high number of cancer patients obtained from high-throughput approaches." (PMID 31311575, 2019). "The induction of FoxM1 by ferritin also may contribute to cancer progression through de-differentiation of tumor cells." (PMID 31366108, 2019). "A pan-cancer analysis revealed FOXM1 regulatory network as a top predictor of poor prognosis." (PMID 31681566, 2019). "Likewise, FOXM1 (Forkhead Box M1), predicted as a target of mtr-miR169k, is among the most overexpressed oncoproteins in many types of cancer and therapeutic interventions to suppress its function are of great interest." (PMID 31850028, 2019). "FOXM1 and Notch1 regulate expression of cell cycle and metabolic genes in cancer." (PMID 31208996, 2019). "Furthermore, we determined FOXM1 isoform expression in GTEx and TCGA normal and TCGA cancer tissues, TCGA paired normal and tumor samples, and human immortalized and cancer cell lines." (PMID 30795624, 2019). "A deregulation of FOXM1 was found in MB and various cancer types (i.e., liver, breast, lung, respectively) where an overexpression of FOXM1 may serve as a biomarker and correlates with poor patient outcome." (PMID 31541075, 2019).
cancer (continued). "The structural picture revealed here of FoxM1 repression provides novel mechanistic insights into transcription factor regulation and may motivate novel cancer therapeutics." (PMID 31134895, 2019). "Moreover, GRB7-mediated ERK/forkhead box M1 (FOXM1) signaling has been suggested to be an oncogenic convergence in the stimulation of cancer invasion." (PMID 31083325, 2019). "Moreover, ChIP assays demonstrated that EPZ treatment significantly abrogated the enriched H3K79 methylation at the FOXM1 promoter induced by cancer serum in BMDCs." (PMID 30628173, 2019). "For instance, overexpression of FOXM1 was reported in cancers of the breast, prostate, and lung." (PMID 30978209, 2019). "Furthermore, we identified FoxM1 as a novel target of E2A and showed that FoxM1 plays a critical role in E2A-regulated inhibition of cancer-initiating capacity." (PMID 31234887, 2019). "Since FOXM1 can promote the proliferation and invasion of cancer cells, it may give rise to the poor prognosis and low survival rate of patients with high FOXM1 expression." (PMID 31886176, 2019). "As DCs play a pivotal role in antitumor immune response, it is questionable whether FOXM1 is a beneficial therapeutic target for cancer treatment." (PMID 30628173, 2019). "As a transcription factor, FOXM1 has many target genes including KIF20A, CENPF, CCNB1, MYC, NIMA-related kinase 2, MMP2, MMP9, and S-phase kinase-associated protein 2 that are implicated in cancer initiation, progression, or drug resistance." (PMID 31072351, 2019). "Additionally, deletion of FoxM1 in cancer cells inhibits tumor development and growth and leads to increased apoptosis." (PMID 31134895, 2019). "Next, we compared FOXM1 expression using previously reported TCGA pan-cancer aneuploidy clusters." (PMID 30795624, 2019). "In addition, due to its clear oncogenic nature FOXM1 has emerged as promissory target for cancer drug therapy." (PMID 30621735, 2019). "FoxM1 was found to be localized in the nucleus and cytoplasm of primary cancer cells." (PMID 30416986, 2018). "So far, several therapeutic strategies have been proposed to target FoxM1 in cancer." (PMID 29765517, 2018). "The expression of FOXM1 may confer genotoxic agent resistance, and its overexpression in DNA-damaging cancer drug-resistant cells has been commonly observed." (PMID 30360388, 2018). "The new results implicating FOXM1 in drug-resistant disease relapse and the β-gal+ phenotype of cellular senescence agree with the well-known pleiotropic function of the transcription factor in cancer cell biology." (PMID 30463534, 2018). "Compared with the non-cancer epithelium, we also found that FoxM1 protein was upregulated in NPC tissues, indicating FoxM1 might be involved in the carcinogenesis of NPC." (PMID 30416986, 2018). "These FOXM1 inhibitors may be used as single agents or in combination with low-dose chemotherapy for cancer treatment." (PMID 30208972, 2018). "As a key oncogene for multiple cancers, FOXM1 inhibitors have been developed to treat cancers." (PMID 29472532, 2018). "In this regard, a protein “forkhead box M1 transcription factor” (FOXM1) over-expressed in a variety of human cancers, and inhibition of FOXM1 by thiostrepton may contribute to the anticancer activity." (PMID 29606130, 2018). "FOXM1 has also been found to promote the proliferation and maintenance of pancreatic, breast and lung cancer stem cells, and its depletion represses the stemness of these cancer cells." (PMID 29180117, 2018). "Moreover, overexpression of FoxM1 is correlated with a clinically aggressive, drug-resistant, cancer phenotype with poor prognosis." (PMID 29707121, 2018).
cancer (continued). "FOXM1 is overexpressed in several types of cancer (prostate, lung, bladder, ovarian, colon, liver, breast stomach and pancreatic cancer) and reduces ROS by means of inducing expression of antioxidant enzymes including catalase, SOD2 and thioredoxin-dependent peroxidase reductase (PRDX3)." (PMID 29760743, 2018). "Consistently, in another dataset from Curtis’s study, FoxM1 was 2.221-fold increase in cancer VS." (PMID 29416660, 2018). "However, the involvement of FoxM1 in cancer lipid metabolism, especially, in the mevalonate pathway of HCC, has not been fully elucidated." (PMID 29765517, 2018). "FOXM1 is frequently overexpressed in a variety of cancers, including CRC." (PMID 30486864, 2018). "However, further evidence shows that FoxM1 is elevated in human cancers, thus questioning its potential for anti-aging therapy." (PMID 30026603, 2018). "Abnormal upregulation of FOXM1 is involved in the oncogenesis of several cancers." (PMID 29587677, 2018). "In this work, c-Myc upregulated the expression of FoxM1 to promote the cancer development which might be used as a target in clinical treatment." (PMID 29554906, 2018). "Therefore miRNA-6852 (SX4) is a novel microRNA differentially regulated by IL-27, which exerts anti-cancer effects by inducing G2/M arrest and cellular necrosis by regulating FoxM1." (PMID 29343703, 2018). "Additionally, FoxM1 expression was found highly increased in the cancer cells migrating into the surroundings and vasculature." (PMID 30416986, 2018). "Taken together, these findings indicate that targeting FOX proteins, especially FOXM1 with RNAi, a technique capable of specificity, may be a potential strategy for cancer therapy." (PMID 30360388, 2018). "Given that FoxM1 acts as a critical master regulator of tumorigenesis and metastasis in human cancers, it is imperative to understand the molecular mechanism of FoxM1 involved in the transcriptional regulation of the diverse signaling pathways in each step of tumorigenesis." (PMID 29423068, 2018). "Therefore, FOXM1 has been identified as a potential therapeutic target for the treatment of cancers." (PMID 30208972, 2018). "This notion of whether FoxM1 and FoxO3a cooperatively regulates the genes required for cell cycle arrest and necrosis in cancer cells warrants further investigation." (PMID 29343703, 2018). "We first compared FOXM1 protein levels between the docetaxel-resistant and parental cancer cells." (PMID 29752436, 2018). "Importantly, a large number of studies have demonstrated that FOXM1 has a strong correlation with divergent kinds of human cancers including RCC." (PMID 29552295, 2018). "It has shown that FOXM1 regulates stemness and survival of cancer cells via several pathways." (PMID 30416986, 2018). "Nevertheless, to date, it has remained unclear whether FoxM1 is involved in the mevalonate pathway of cholesterol biosynthesis, which is known to play a crucial role in lipid metabolism in cancer." (PMID 29765517, 2018). "We thus demonstrate a novel and specific mechanism for FOXM1 inhibition by honokiol, which partially may explain its anticancer activity in cancer cells." (PMID 29367668, 2018). "In this context, it is not surprising that FOXM1 serves as proto-oncogene in most cancers and aberrant expression or mutations constitute the origin of many treatment resistance mechanisms." (PMID 29959570, 2018). "For example, FOXM1 is currently regarded as an essential regulator of various cancers." (PMID 30360388, 2018). "Oncogenic transcription factor FOXM1 is one of the most overexpressed oncoproteins in human cancer." (PMID 29367668, 2018). "Moreover, FoxM1 conferred the self-renewal properties of cancer cells by increasing side populations (SP) cells and formed larger and more tumor spheres." (PMID 30416986, 2018).
cancer (continued). "Therefore, targeting FoxM1 expression can lead to inhibition of these invasion and migration properties of cancer cells." (PMID 29707121, 2018). "Some studies have demonstrated FOXM1-targeted therapy could effectively restrain tumor development of cancer." (PMID 28427178, 2017). "The obtained FOXM1-Apt could be used as a probe for FOXM1 detection and an inhibitor of FOXM1 transcriptional function in cancer cells at the same time, providing a potential reagent for cancer diagnosis and therapy in the future." (PMID 28358012, 2017). "Knockdown of SMYD2 abolished β-catenin methylation and nuclear localization of β-catenin through the loss of the interaction with FOXM1, resulted in the downregulation of the Wnt/β-catenin/TCF downstream genes such as c-myc and cyclin D, and subsequently induced cancer cell death." (PMID 28915556, 2017). "The lysosomal- dependent regulation of FoxM1 by chemicals might be a new strategy for down-regulating oncogenic transcription factor FoxM1 as a strategy to combat cancer." (PMID 28378765, 2017). "An overexpression of FOXM1 has been detected in a broad range of human cancers, including RCC." (PMID 28902136, 2017). "Our results suggest that the obtained FOXM1 Apt could be used as a probe for FOXM1 detection and an inhibitor of FOXM1 transcriptional functions in cancer cells at the same time, providing a potential reagent for cancer diagnosis and treatment in the future." (PMID 28358012, 2017). "Increased FoxM1 expression contributes to cancer cell invasiveness." (PMID 29212236, 2017). "Taken together, these results determined that FOXM1 Apt could suppress the cellular proliferation of cancer cells by abolishing the functions of FOXM1 in vivo." (PMID 28358012, 2017). "Moreover, several other previous studies have also reported that enhanced levels of FoxM1 led to cancer cell migration, invasion and metastasis via regulating signal pathways or inducing the epithelial-to-mesenchymal transition." (PMID 28767320, 2017). "Therefore, FOXM1 Apt obtained from this study provided a potential reagent to detect and repress FOXM1 at the same time, good for cancer diagnosis and treatment in the future." (PMID 28358012, 2017). "These evidences suggest FOXM1 may be an attractive prognostic prediction biomarker and therapeutic target for human cancers." (PMID 28427178, 2017). "Another possible explanation may be that FOXM1 is a multifaceted player in cancer, and interacts with different signaling pathways that may convey opposite effects according to which specific cellular model is involved." (PMID 28482906, 2017). "Recent evidence also suggests that FOXM1 has a role in cancer invasion and angiogenesis." (PMID 28199985, 2017). "The FOXM1 transcription factor is a proto-oncogene involved in cell cycle progression, cell proliferation, tumorigenesis and cancer progression, and many of its target genes (> 20) were downregulated in paclitaxel-residual MDA-MB-231 cells including AURKB, CCNB1, PLK1, PLK2, and the kinesin KIF20A." (PMID 28187446, 2017). "The transcription factor FoxM1 is a driver of cancer progression." (PMID 28387346, 2017). "Moreover, the prognostic value of FOXM1 has been reported in several cancer types with the observation that FOXM1 activity is more predictive to prognosis than its mRNA level." (PMID 29100329, 2017). "We also tested whether a FOXM1 inhibitor used as a chemosensitizer may restore paclitaxel sensitivity in cancer cells." (PMID 28277541, 2017). "Thus FOXM1 is considered a promising target for therapeutic intervention in cancer, and its inhibitors, siomycin A and cell-penetrating ARF peptide, induce cancer cell apoptosis." (PMID 28199985, 2017). "The aberrant overexpression of FOXM1 correlates with tumorigenesis and progression of many cancers." (PMID 28358012, 2017).